PFPLP (pore forming protein like, pseudogene)
Synonyms: MPEG2P
Gene: Processed pseudogene on chromosome 11 (59,287,339 to 59,289,486, reverse strand). Ensembl gene ENSG00000254704.
Diseases named in the same sentence as PFPLP in open-access papers:
PFPLP is named in the same sentence as 2 diseases in open-access papers, as found by Europe PMC text mining. Sharing a sentence is not in itself a finding about the gene and the disease. The quoted sentences say what the papers report.
anemia (1 paper, 2020). A reduction in the number of red blood cells, the amount of hemoglobin, and/or the volume of packed red blood cells. "Our study supports the role of PfPLP in inducing premature senescence of erythrocytes leading to anemia in severe malaria." (PMID 32266171, 2020).
PFPLP also shares sentences with these, for which no sentence is quoted: malaria (1 paper).